TLR7 (toll like receptor 7)
Diseases named in the same sentence as TLR7 in open-access papers (continued):
Sharing a sentence is not in itself a finding about the gene and the disease.
vitamin D deficiency (1 paper, 2024). A nutritional condition produced by a deficiency of VITAMIN D in the diet, insufficient production of vitamin D in the skin, inadequate absorption of vitamin D from the diet, or abnormal conversion of vitamin D to its bioactive metabolites. "Further research could also consider the effect of TLR7 on other pathways involved in the amplification of the Th2 response, such as IL-13, IL-31, and IL-33 cytokines, vitamin D deficiency, and changes in the lung microbiome, in the context of chronic respiratory disease." (PMID 39769461, 2024).
tumor (520 papers, 2007 to 2026). "At the topical tumor site, local immune activation by IMQ stimulates c-Jun/AP-1 signaling in IFN-I primed and TLR7-expressing DCs to produce interleukin (IL)-12, which impairs tumor-associated angiogenesis and induces necrosis at the treated site." (PMID 39849091, 2025). "One example is a trastuzumab biosimilar conjugated to a Toll-like receptor 7/8 (TLR7/8) agonist, designed to activate APCs and potentially overcome therapeutic resistance associated with tumor heterogeneity." (PMID 41425250, 2025). "Specifically, TLR7 was identified as a prognostic biomarker, where lower expression in tumor tissues was linked to worse outcomes." (PMID 39857735, 2025). "Concurrently, R848 self-assembled nanoparticles have emerged as potent immunomodulators, significantly enhancing anti-tumor immunity by synergistically activating TLR7/8 pathways and re-polarizing tumor-associated macrophages." (PMID 40648713, 2025). "TLR7, in particular, has been implicated in the activation of type I interferons and the promotion of anti-tumor immunity." (PMID 40438106, 2025). "ISACs conjugated with TLR7/8/9 agonists have shown the ability to reprogram tumor-associated macrophages and activate dendritic cells, resulting in robust T cell-mediated tumor regression in melanoma and breast cancer models." (PMID 40003906, 2025). "In this study, we aimed to investigate the anti-tumor activity in combination of TLR7 agonist, DSP-0509, with RT and underlying mechanism." (PMID 39054418, 2024). "TLR7 stimulation has been shown to activate dendritic cells and promote the cross-presentation of tumor-associated antigens, leading to the activation of cytotoxic T lymphocytes and anti-tumor immunity." (PMID 38903515, 2024). "Using a TLR7-deficient mouse model, we observed that TLR7 deficiency promotes tumor growth and decreases survival rates." (PMID 38476365, 2024). "As a result of the intratumoral TLR7 agonist treatment, the number of M1 macrophages was increased, while the number of M2 macrophages associated with the tumor was reduced." (PMID 36851155, 2023). "Toll-like receptor 7 and 8 (TLR7/8) agonist was also delivered, showing a high M2/M1 tumor-associated macrophage ratio." (PMID 37110674, 2023). "The TLR7 agonist imiquimod can be released from these particles in the cytoplasm to reprogram M2-like tumor-associated macrophage." (PMID 36365103, 2022). "CRC-derived sEVs containing miR-21 help polarize liver macrophages into an IL-6-secreting phenotype by binding to TLR7 (Toll-like receptor 7) in tumor-associated macrophages, contributing to the inflammatory environment." (PMID 35163305, 2022). "recently demonstrated that a TLR7/8 agonist enhances polarisation of tumour-associated macrophages, hence enhancing anti-tumour therapy, but the detailed mechanism still needs further detection." (PMID 35801728, 2022). "Following a single IT dose, TransCon TLR7/8 Agonist mediated potent tumor growth inhibition which was associated with sustained resiquimod release over several weeks with minimal induction of systemic cytokines." (PMID 36123697, 2022). "Although the present results demonstrated that TLR7/8 agonists alone or as an adjuvant can retard tumor growth, other studies have suggested that TLR7 is associated with carcinogenesis and immunosuppression." (PMID 36476317, 2022). "Marked differences are observed between treatments, including decreased tumor-associated macrophages upon TLR7 agonist treatment." (PMID 34381732, 2021). "TLR7 activation by imiquimod caused human DCs to become tumoricidal, possibly by triggering tumor-specific cytolytic T-cells and activation of antigen presentation." (PMID 34715891, 2021). "TLR7 enabled tumor-associated effector pDCs to educate NK cells, mDCs, as well as activation of CD8+ T cells." (PMID 34124272, 2021). "Previous studies have reported that TLR7 agonists inhibit tumor migration by activating PKA and promoting glioma‐associated oncogene (GLI) phosphorylation." (PMID 33463061, 2021).
tumor (continued). "Despite the antitumor effects of TLR7 activation, recent studies underlined its potential tumor-promoting role." (PMID 34573939, 2021). "One of the possible approaches is the therapeutic activation of tumor-associated pDCs using TLR7 and TLR9 agonists." (PMID 32054102, 2020). "Other studies have revealed that the recruitment of pDCs and the production of type I IFNs can be enhanced by a TLR7 agonist (imiquimod), which causes tumor regression by creating an inflammatory environment." (PMID 32012718, 2020). "It has been proposed that exosomal miRNAs such as let-7, miR-21, and miR-29a, identified in oEVs, can act as an unconventional mode to activate TLR7 in mice and cause neurodegeneration and tumor growth and metastasis." (PMID 32075098, 2020). "Topical delivery to the site of the tumor suggests the mode of action is primarily the maturation of tumor-associated DC, particularly pDC, which express high levels of TLR7." (PMID 30979057, 2019). "A high TLR2 and a high TLR4 expression associated with pT2–4 tumours (p = 0.043; p = 0.049), and a high TLR7 expression associated with pT3 tumours (p = 0.025)." (PMID 31467388, 2019). "Several recent studies highlight the dual potential for benefit and harm of TLR7 agonists, which hold substantial promise as anti-tumor agents but cause acute toxicities." (PMID 31615993, 2019). "Our laboratory has attempted to construct vaccines by conjugating TLR7 agonists with tumor-associated antigens." (PMID 29739434, 2018). "Tumor-associated pDCs then respond to malignant-derived immunosuppressive factors during the disease process through regulatory factors from TLR-7/9 signaling pathways and components produced by pDCs." (PMID 29085361, 2017). "Importantly, the downregulation of TLR7 expression was associated with a shift from an immunologically dominant tumor microenvironment to a metabolically dominant state." (PMID 39857735, 2025). "In tumor-associated DCs, combined applications of TLR7/8 agonists and STAT3 inhibitors effectively enhance the antigen uptake and presentation by DCs, which thus promotes DC migration to lymph nodes and augments the antigen-specific cytotoxic activity of CD8+ T cells." (PMID 41293166, 2025). "In addition, the reduction in tumor growth and improved survival from intratumoral administration of the unadjuvanted vaccine was found to be diminished in TLR7-deficient mice." (PMID 38476365, 2024). "Further, we could confirm the potential of CB-pDCs to promote inflammation in the tumor microenvironment by eliciting cytokines associated with NK and T cell recruitment and function upon TLR7 stimulation ex vivo in patient tumor explants." (PMID 39575246, 2024). "Moreover, high TLR7 expression in primary human tumor tissue samples was associated with significantly shortened survival." (PMID 36602302, 2023). "Additionally, TLR7 expression has been linked to tumor progression, inflammation, and decreasing the anti-tumoral molecules in murine models and overexpression of TLR7 has been reported in human PDAC." (PMID 35536778, 2022). "SZU-106, a small-molecule TLR7 agonist, linked to the cell surface with a pegylated linker to produce a novel whole-tumor-cell vaccine, showed immune-activating responses in both in vitro and in vivo experiments, with a great potential to treat advanced malignant tumors." (PMID 36476317, 2022). "Islam and coworkers reported that mice vaccinated with LNP-encapsulated OVA-expressing mRNA and the chemically modified TLR7/8 agonist C16-R848 exhibited increased tumor-associated antigen presentation, antigen-specific CD8+ T cell recruitment, and anti-tumor activity." (PMID 36291194, 2022). "In future studies, we will conjugate the TLR7 agonists to other tumor-associated antigens, especially macromolecular protein antigens, where SZU251 could be more convenient for conjugation than SZU101." (PMID 36499455, 2022).
tumor (continued). "Forodesine is approved in Japan for the treatment of PTCL and exhibits antitumor activity in a subset of patients, but it is unclear whether tumor cell lethality or TLR7 agonism underlies this effect." (PMID 35653193, 2022). "Furthermore, the addition of TLR7 agonists progressed the proportion of M1 to M2 tumor-associated macrophages (TAMs) and promoted the infiltration of tumor-specific IFNγ -producing CD8+ T cells." (PMID 35745800, 2022). "Besides, the authors found that a TLR7 activation leads to an acceleration of tumor formation, and pharmacological inhibition of TLR7 was associated with decreased tumor growth." (PMID 34573939, 2021). "In certain cancers, synthetic TLR7/8 agonists have been shown to cause apoptosis of tumor cells." (PMID 34058283, 2021). "Likewise, intratumor administration of the TLR7 agonist 1V270 increased the ratio of M1 to M2 tumor-associated macrophages and was associated with improved survival." (PMID 33679711, 2020). "Similarly, tumor-associated pDCs showed decreased IFNα secretion upon TLR7 and TLR9 stimulation in breast and ovarian cancers." (PMID 30987228, 2019). "The correlation between CDSE1 and TLR4, TLR7 or TLR8 expression suggests that PDAC patients with high UNR/CDSE1 expression may present a less aggressive tumor phenotype, more susceptible to be cleared by the immune response." (PMID 28763470, 2017). "Here we showed that a conjugate of exogenous purified recombinant OCT4 protein covalently linked to a TLR7 agonist (T7-OCT4) could elicit a surprisingly strong anti-tumor effect on EC tumors by inducing tumor-specific immune response." (PMID 25990580, 2015). "For example, previous studies showed that the combination of STING agonists and TLR7/8 agonists can cause stronger antigen cross-presentation in tumor immunotherapy, leading to significant tumor regression, and has a better anti-tumor effect than single-agent therapy." (PMID 41516215, 2025). "Moreover, TLR7 signaling has been associated with the activation of dendritic cells and the subsequent initiation of adaptive immunity, both of which are crucial for an effective anti-tumor response." (PMID 40438106, 2025). "Moreover, tumor cell TLR7 expression inversely associated with patients’ survival." (PMID 33578955, 2021). "In particular, an intact and afucosylated Fc glycan is essential for robust tumor-cell killing and cytokine induction, while cleavable linkers further enhance innate immune activation through efficient intracellular release of the TLR7/8 agonist." (PMID 42320630, 2026). "In the case of R848, as a TLR7/8 agonist, it is clearly established as an immune stimulant with recognized anti-tumor activity." (PMID 41550509, 2026). "In prostate cancer, activation of TLR2, TLR4, and TLR9 stimulates tumor growth while activation of TLR3, TLR4, TLR5, and TLR7 suppress tumor development." (PMID 41601666, 2026). "It stimulates the production of pro-inflammatory cytokines, including IFN-α, IL-6, and TNF-α, and activation of TLR7/8 promotes a Th1-mediated anti-tumor response dependent on IFN-γ." (PMID 41601666, 2026). "Concurrently, SHINE facilitates the controlled release of the TLR7/8 agonist R848 and, through surface-conjugated anti-PD-L1 antibodies, enables immune checkpoint blockade and enhances active tumor targeting." (PMID 42099773, 2026). "A similar mechanism occurs in CRC, where tumor-derived EVs enriched with miR-21-5p interact with TLR7 on Kupffer cells in the liver, driving macrophage polarization and IL-6 secretion." (PMID 40574836, 2025). "For instance, ISACs bearing TLR7/8/9 agonists activate dendritic cells, enhancing antigen presentation to T cells and, as a consequence, the generation of potent tumor-specific cytotoxic T cell responses, which is required for long-term control of the tumor." (PMID 40003906, 2025).
tumor (continued). "In this context, TLR7/8 agonists—either as monotherapies or in combination with other immunostimulatory agents—have demonstrated the ability to suppress tumor growth and enhance immune activation." (PMID 41228373, 2025). "Additional innate immune activation by combination therapy with an imidazoquinoline TLR7/8 agonist greatly improves tumor eradication, thereby confirming similar studies." (PMID 40230629, 2025). "In CRC, tumor EVs enriched with miR-21-5p similarly engage TLR7 on liver Kupffer cells, inducing them to produce IL-6 and adopt an M2 polarization, thereby establishing an inflammatory, tumor-promoting niche in the liver." (PMID 40574836, 2025). "In another study, a tumor-targeting LIV1 antibody was conjugated with TLR7/8 agonists to assess antitumor responses." (PMID 41228373, 2025). "Conversely, blockade of TLR7 protected against carcinogenesis; hence, high TLR7 tone maintains an immunosuppressive tumor-permissive TME, whereas inhibition of that pathway delays tumor development." (PMID 41465346, 2025). "Because these treatments promote the release of tumor antigens, combining them with TLR7/8 agonists can result in the activation of antigen-specific immune response and long-term antitumor immunity." (PMID 41228373, 2025). "TLR7 can drive the production of type I interferons, which are essential for the anti-tumor efficacy of RNA vaccines." (PMID 40333256, 2025). "For example, administering the Toll-like receptor 7 (TLR7) agonist imiquimod requires the simultaneous inhibition of iNOS activity to promote tumor antigen-specific Th1 responses and suppress tumor growth in vivo." (PMID 40642105, 2025). "applied a cholesterol-conjugated TLR7 agonist liposome in combination with radiotherapy in a mouse model, demonstrating that this combined strategy significantly inhibited tumor growth and induced anti-tumor immune responses." (PMID 41488647, 2025). "852A, the TLR7 agonist prevents in vitro proliferation of some tumor cells (Hs294T and 769‐P) and delays tumor growth in vivo in a DCs and interferon‐α‐dependent manner." (PMID 40396589, 2025). "For example, protease-activated TLR7/8 ligands conjugated to tumor-targeting antibodies enable tumor site-restricted activation of DCs, minimizing systemic cytokine storms." (PMID 41030952, 2025). "TLR7 agonists are capable of inducing certain cytokine responses that promote changes in the tumor microenvironment and enhance the cytotoxicity of systemic antitumor CD8+ T cells." (PMID 39857735, 2025). "Combining chemotherapeutic agents with TLR7/8 agonists has shown enhanced therapeutic efficacy by simultaneously promoting tumor cell death and immune activation." (PMID 41228373, 2025). "Mechanistically, oral IMQ activates pDC to produce IFN-I, which then exerts a profound impact on the tumor microenvironment (TME) by inducing TLR7/8 expression on DCs and macrophages in both mice and in patients." (PMID 39849091, 2025). "TLR7 signaling can also suppress anti-tumor immune cells through cytokine production, notably IL-10." (PMID 41157253, 2025). "TLR7 inversely correlated with tumor purity, and positively with B cells, CD8+ T cells, CD4+ T cells, macrophages, neutrophils, and dendritic cells." (PMID 39857735, 2025). "Enrichment analysis, the Tumor Immune Estimation Resource database, and single-sample gene set enrichment analysis were used to explore TLR7’s potential function." (PMID 39857735, 2025). "IQ (a TLR7 agonist) was combined with DOX to enhance tumor-specific immune activation through memory T cell proliferation and dendritic cell (DC) maturation." (PMID 41228373, 2025). "CD11c+ DCs in peripheral blood can activate toll-like receptor 7 (TLR7) to trigger the production of ROS, driving the TLR7/mROS/IL-12 axis to enhance the tumor-killing ability of NK cells." (PMID 40303301, 2025).